MYC (MYC proto-oncogene, bHLH transcription factor)
Diseases named in the same sentence as MYC in open-access papers (continued):
Sharing a sentence is not in itself a finding about the gene and the disease.
lymph node metastasis (30 papers, 2000 to 2024). "MYC amplification is shown to be associated with lymph node metastasis and poor prognosis in ESCC48." (PMID 34285259, 2021). "Regarding c-MYC, a positive association with the lymph node metastasis (p = 0.027, n = 25) was found; that is, the levels of c-MYC RNA are higher in cats with the tumours and lymph node metastasis." (PMID 31461477, 2019). "An increase in MYC mRNA level was associated with the presence of lymph node metastasis (p = 0.016) and GC tumor stage III-IV (p = 0.036)." (PMID 24053468, 2013). "Tumors harboring MYC gain or amplification were less likely to develop lymph node metastases (9% vs. 57% if copy number neutral, p = 0.018)." (PMID 35792986, 2022). "High expression of MYC was associated with advanced pTNM-stage (P=0.011), and PDIA3 and ITGA5B1 were correlated with both lymph node metastasis (PDIA3: P < 0.001; ITGA5B1: P=0.001) and pTNM-stage (PDIA3: P=0.001; ITGA5B1: P=0.009)." (PMID 31886273, 2019). "Positive associations were found between tumour size and YBX1 RNA, and lymph node metastasis with c-MYC RNA levels." (PMID 31461477, 2019). "For analysis the locational heterogeneity of c-MYC and ß-catenin expression, we investigated cancer from three lesion, including the primary, distant and lymph node metastasis (cohort 2)." (PMID 27619912, 2016). "In 142 lymph node metastases, we performed c-MYC and ß-catenin analysis in 111 cases which paraffin blocks were available." (PMID 27619912, 2016). "To evaluate the regional heterogeneity of c-MYC status, we examined tissue from 3 sites including the primary cancer, distant metastasis, and lymph-node metastasis for each patient with advanced CRC (cohort 2)." (PMID 26426996, 2015). "The MYC expression was not significantly correlated with age and lymph node metastasis of HCC patients but was significantly linked to tumor diameter, differentiation level, and TNM stage." (PMID 36033372, 2022). "Patients with high expression of c–MYC were likely to develop lymph node metastasis." (PMID 35008557, 2021). "Furthermore, lymph node metastasis was positively associated with c-MYC expression; an association also found for c-MYC protein levels in HBC patients." (PMID 31461477, 2019). "In addition to the Shannon index for c-MYC copy number, high T stage, lymph node metastasis, and lymphovascular invasion were found to be significant prognostic factors in univariate analyses." (PMID 29228597, 2017). "However, when c-MYC-amplified cases were excluded, lymph node metastasis (p=0.005) and high Shannon index (p=0.046) also proved to be independent prognostic indicators of adverse outcome." (PMID 29228597, 2017). "In addition, FBXW7 mRNA expression deregulation was associated with the presence of lymph node metastasis and GC stage III-IV, as was also observed with MYC mRNA." (PMID 24053468, 2013). "Moreover, deregulated MYC and FBXW7 mRNA expression was associated with the presence of lymph node metastasis and tumor stage III-IV." (PMID 24053468, 2013). "Next, a comparative analysis of the cell cycle in the primary tumor and lymph node metastasis showed that the two CSC-like clusters (HMGA1-high and CD44/MYC-high) had an increased cell division index in lymph node metastasis." (PMID 35611554, 2022). "Lymph node metastasis of 3 (15.8%), 2 (10.5%) and 2 (10.5%) patients exhibited amplifications in all 3 exons of ERBB2, CCND1 and MYC, respectively." (PMID 33298978, 2020). "Discordance between c-MYC GCN gain in the primary tumor and lymph-node metastasis was detected in 24/79 (30.4%) cases." (PMID 26426996, 2015). "Lymph-node metastasis was observed in 79 of 152 advanced CRC patients and c-MYC GCN gain was observed in 18 (22.8%) of these cases." (PMID 26426996, 2015). "c-MYC GCN gain (tissue ddPCR) may be correlated with tumor a location of the ascending to descending colon (P = 0.023) and lymph node metastasis (P = 0.028)." (PMID 30733532, 2019).
lymph node metastasis (continued). "In addition, MYC overexpression was related to large tumor size, high histologic grade, lymph node metastasis, negative hormone receptors and positive Ki67 expression." (PMID 29212204, 2017). "In addition, to our knowledge, this is the first study to report an association between increased MYC mRNA expression and the presence of lymph node metastasis and CG stage III-IV, reinforcing the idea that MYC deregulation is a strong factor for malignancy in GC." (PMID 24053468, 2013).
diabetes (29 papers, 2012 to 2026). "For instance, in MycERTAM mice that express switchable MYC in pancreatic β-cells, MYC activation is sufficient to drive the cells into cell cycle, but unfettered proliferation is constrained by subsequent apoptosis, which quickly results in β-cell loss and diabetes." (PMID 38510176, 2024). "Overexpression of MYC in cellular and animal models has led to increased beta cell proliferation, apoptosis and down-regulation of insulin gene leading to diabetes." (PMID 39464889, 2024). "Treatment with the MYC-signaling inhibitor KJ-Pyr-9, diabetes medication metformin and chemotherapeutic agent carboplatin significantly reduced the cell survival of ECSCs." (PMID 35269569, 2022). "Of note, recent studies showed that the diabetes drug metformin substantially suppressed MYC expression, reduced GLS activity, and inhibited autophagy in tumor cells 45-47." (PMID 34335968, 2021). "Our results are opposite to those of some previous studies that observed that MYC gene expression is highly upregulated in diabetes." (PMID 32823525, 2020). "Compared with these emerging drug developments, metformin has several advantages as a MYC inhibitor: (a) As a first‐line drug treating diabetes, metformin is safe, and its side effects are well characterized." (PMID 30221473, 2018). "Although not identified by 2D-DIGE as differentially expressed in experimental diabetes, MYC, along with EGR1 and the AP-1 subunit c-Fos, emerged as interconnected nodes following interrogation of differentially expressed proteins using MetaCore software." (PMID 25080971, 2014). "In order to support this notion, the group of Valera induced diabetes in c-MYC transgenic and control mice by short-term (seven days) streptozotocin (STZ) treatment, a compound that has a preferential toxicity towards pancreatic β-cells, leading to their destruction and absence of insulin." (PMID 28422055, 2017). "They clearly show that c-MYC overexpression in livers of transgenic mice prevented the development of diabetes following streptozotocin (STZ) treatment, not only by inducing hepatic glucose uptake and utilization, but also by blocking gluconeogenesis and ketogenesis." (PMID 28422055, 2017). "Diseases in which MYC activation may instead be desired include those where stimulation of cell proliferation and tissue regeneration is needed, such as after ischaemic damage in the heart, diabetes, and neuronal repair." (PMID 38510176, 2024). "Likewise, the genomic region within UPF1 gene, covering the top-ranked CpG site is associated with CTCF, Egr1, and two more transcription factors: MYC—involved in the pathogenesis of diabetes, and PU1—initiating insulin resistance as well as regulating lipolysis." (PMID 30545422, 2018). "MYC and SLC7A11 were particularly notable, showing upregulated expression in DR samples and involvement in apoptosis and diabetes-related pathways." (PMID 39634176, 2024). "A previous study reported that eucalyptol inhibited protein expression of MYC in AGE-treated podocytes and diabetic kidneys." (PMID 36331666, 2022). "TF prediction analysis showed that NR3C1, TEAD and TFs that cooperate with YAP-TEAD, such as Klf4, SP1, AP1, MYC and ZEB1, were enriched in the DEGs of the diabetes vs. control comparison." (PMID 34970541, 2021). "In healthy cells, MYC can activate PI3K/AKT pathway, whereas accumulating evidence has demonstrated that inactivated PI3K/AKT pathway is related to diverse biological events, such as high-glucose increased metastasis, diabetes, and bone differentiation." (PMID 32522250, 2020). "Thus, the destabilization of MYC/MYCN by metformin and phenformin and the ability of metformin to upregulate tumor suppressor genes may partly explain why these diabetes drugs protect against cancer incidence and mortality." (PMID 24190252, 2014).
diabetes (continued). "Altogether, these results using c-MYC overexpression reinforce the role of hepatic c-MYC in maintaining glucose homeostasis, and suggest that the increase of glucose uptake and utilization could be a useful therapeutic approach for the treatment of diabetes mellitus." (PMID 28422055, 2017).
ovarian tumors (29 papers, 2003 to 2025). "c-MYC transcript and protein levels are higher in ovarian tumors compared to normal tissues, and c-MYC overexpression is associated with more aggressive disease." (PMID 36765581, 2023). "Interestingly, activation of FOXO3 nuclear localization and consequent inhibition of the expressions of stemness markers, including Nanog, Oct4, and c-MYC, are caused by inhibition of the formation of ovarian tumor spheroids." (PMID 32899775, 2020). "The oncogenic transcription factor MYC has been reported to be overexpressed at the RNA level in up to 60% of ovarian tumors." (PMID 39831777, 2025). "We determined that pluripotency factors KLF4 and MYC were upregulated in carboplatin-resistant ovarian tumor tissue compared to sensitive tumor tissues." (PMID 38796478, 2024). "Integrated genome analysis has reported that the MYC gene is amplified in 30–40% of human ovarian tumors." (PMID 33671595, 2021). "Co-amplified genes were also prominent in the high-risk ovarian tumors including case OC-04 with high level CCNE1 amplification and co-amplification of CCND1, CCND3, MYC and ETV6 genes." (PMID 23289505, 2013). "Additional targets of the HSF1 and MYC complex could offer some insights to their functions in ovarian tumors." (PMID 39831777, 2025). "Since ODC transcription is upregulated by the oncogenes, MYC and RAS, the association of high levels of MYC and mutant RAS in ovarian tumor cells resistant to PARP inhibitors and platinum-based chemotherapy may be mediated, at least in part, by polyamines." (PMID 35736348, 2022). "In addition, a treatment of ovarian tumors with BETi suppresses MYC activity, by impairing MYC gene expression." (PMID 34758842, 2021). "We compared the target genes identified from normal ovarian cells by the O’Mara group and ovarian tumor cells from our study and found some common targets like ABO at 9q34.2, MYC at 8q24.21, and METTL10 at 10p12.31." (PMID 33815481, 2021). "In addition to MYC, copy-number amplification and/or overexpression of MYCL1 and MYCN have also been reported in ovarian tumors." (PMID 33671595, 2021). "Likewise, genes frequently amplified (MYC, PIK3CA and AURKA) or lost (RB1, PTEN) in ovarian tumours were also commonly multiplied or lost in our set of patient cells." (PMID 29180611, 2017).
liver fibrosis (28 papers, 2015 to 2025). "In human patients, MYC triggers hepatocyte proliferation and is associated with liver fibrosis." (PMID 28871112, 2017). "MYC is involved in hepatocellular proliferation, and overexpression in hepatocytes leads to increased liver fibrosis." (PMID 40087773, 2025). "Research has found that the SIRT2/ERK/c-MYC axis plays a crucial role in promoting liver fibrosis, and SIRT2 inhibitors are a potential new strategy for treating liver fibrosis and cirrhosis." (PMID 39226168, 2024). "In patients with advanced stages of ALD, MYC is strongly upregulated and correlates with the progression of liver fibrosis." (PMID 38510176, 2024). "This link between MYC and hepatic fibrosis is reinforced by the fact that MYC mRNA expression was found to be upregulated in patients with liver cirrhosis." (PMID 38510176, 2024). "One study identified butyrate as a protective agent for diet-induced non-alcoholic hepatic steatosis and liver fibrosis by downregulating, among other, MYC." (PMID 36571600, 2023). "Recently, we showed that overexpression of c-MYC is frequently detected in patients with advanced stages of liver fibrosis and in experimental models of hepatic fibrosis." (PMID 28422055, 2017). "Among six potential transcription factors (conserved between mice and humans) that bind at the proximal promoter region of the identified BCL2 gene, we focused on c-MYC as it is known to modulate liver fibrosis and is regulated by miR-122 through E2F1 and TFDP2 in mouse hepatic cells." (PMID 32650615, 2020). "Emerging data suggests that deregulation of c-MYC function might be associated not only with HCC development, but also with chronic liver disease, such as ALD, viral hepatitis, liver fibrosis/cirrhosis and HB)." (PMID 28422055, 2017). "Additionally, gerbils fed with a high-fat and high-cholesterol diet showed increased hepatic USP33 expression, whose modulation revealed a signal transduction pathway regulated by both this enzyme and MYC, which controls activation of HSCs, the main cells responsible for liver fibrosis." (PMID 38510176, 2024). "Also of note is the pronounced deactivation of MYC upon BU treatment, as confirmed by a decrease in cMyc protein expression with western blot analysis, since this has been demonstrated to be a marker of liver fibrosis and overexpression of MYC alone induces HSC activation." (PMID 34944770, 2021). "The results revealed that quercetin and luteolin could activate the PI3K-Akt signaling pathway and inhibit liver fibrosis by binding to hub targets, including AKT1, CCND1, EGFR, MAPK1, MYC, and RELA." (PMID 37083803, 2023). "Finally, we determined the expression of c-MYC in liver samples from six patients with MAFLD and advanced liver fibrosis (F3–F4)." (PMID 35008356, 2021).
retinoblastoma (28 papers, 2002 to 2025). A malignant tumor that originates in the nuclear layer of the retina. "To mimic MYCN over-expression after copy number MYCN-mutations in retinoblastoma, we used the genome-integrating piggyBac expression system to generate stable and cell-ubiquitous expression of human MYC-sequences in chicken retinal cells." (PMID 35729105, 2022). "MYCN-overexpressing retinoblastoma cells (MYCNO/E-cells) demonstrated remarkable sensitivity to MYC-targeting therapies, particularly transcriptional inhibitors such as THZ1 (a selective CDK7 inhibitor) and Flavopiridol (a broader-spectrum CDK inhibitor)." (PMID 40943594, 2025). "Transcriptomic profiling demonstrated that MYCN-overexpressing organoids closely recapitulated molecular features of patient-derived MYCN-amplified retinoblastomas, particularly through activation of MYC/E2F and mTORC1 signaling pathways." (PMID 40943594, 2025). "Recent molecular characterisation has separated Pinealoblastoma (PB) into five molecular subgroups: PB-Group 1, PB-Group 2, PB-Group 3, retinoblastoma (RB) and MYC; each with distinct clinico-pathological and survival characteristics." (PMID 40556803, 2025). "This selective sensitivity likely reflects a heightened dependency of these cells on MYC-driven signaling (‘oncogene addiction’), emphasizing the vulnerability of retinoblastoma cells primarily driven by MYCN amplification." (PMID 40943594, 2025). "MYCN over-expression transforms retinal progenitor cells for cPRs and HCs, implicating the progenitors as the cell-of-origin for this subtype of MYC-induced retinoblastoma in chicken retina and in human retinal organoids." (PMID 35729105, 2022). "In studies establishing that MDM2 regulates MYCN in retinoblastoma, we noticed that retinoblastoma cell line RB176 expressed MYC in addition to MYCN." (PMID 33425720, 2020). "The other retinoblastoma had multiple genomic abnormalities on chromosomes 6, 7, and 8, in line with chromothripsis, chromoanasynthesis or chromoplexy including an amplification containing the downstream MYC(N) signaling component, BRAF." (PMID 39079981, 2024). "By using the ubiquitous CAG promotor, the stage- and tissue-specificity of MYC expression was over-ridden, providing an explanation for how c-MYC could drive the phenotype despite c-MYC mutations not being common in retinoblastoma." (PMID 35729105, 2022). "The enrichment of genes associated with MYC-targets might indicate that deregulation of gene expression by MYCN could be an important factor in retinoblastoma development, strengthened by rare retinoblastoma entities in which MYCN amplification substitutes for mutational RB1 inactivation." (PMID 35565295, 2022). "DNA methylation profiling reveals three subtypes and two new subgroups that are exclusively present before 7 year of age: (i) Pinealoblastoma-RB displays similarities with retinoblastoma and, (ii) Pinealoblastoma-MYC when MYC activation is present." (PMID 32676456, 2020). "The focal 13q31.3 amplification in 1 retinoblastoma harbored MIR17HG, a microRNA known to activate MYC(N) signaling, and part of GPC5." (PMID 39079981, 2024). "Accordingly, the MYC-target gene PLK1 was one of the top upregulated genes in RB1ko, which fits the anti-proliferative effect of PLK1-inhibition in retinoblastoma cell lines." (PMID 35565295, 2022). "The regulatory specificity was best illustrated in retinoblastoma cell line RB176, in which MYCN and MYC are co-expressed yet MDM2 was needed to sustain only MYCN." (PMID 33425720, 2020). "We report that MYC and MYCN show consistently different dependence on MDM2 in cancer cell lines, yet similar abilities to induce MDM2 expression and MDM2-dependent proliferation in the retinoblastoma cell of origin." (PMID 33425720, 2020). "We also assessed whether ectopic MYC and MYCN induce MDM2 in a manner that is critical to the onset of tumorigenesis in an intact retina model of retinoblastoma initiation." (PMID 33425720, 2020).
retinoblastoma (continued). "Conversely, ectopic overexpression of MYC as well as MYCN induced high-level MDM2 expression and gave rise to rapidly proliferating and MDM2-dependent cone-precursor-derived masses in a cultured retinoblastoma genesis model." (PMID 33425720, 2020).